MAGEA6 (MAGE family member A6)
Diseases named in the same sentence as MAGEA6 in open-access papers (continued):
Sharing a sentence is not in itself a finding about the gene and the disease.
cancer (35 papers, 2012 to 2025). A tumor composed of atypical neoplastic, often pleomorphic cells that invade other tissues. "In summary, our data show that cancer-specific mutations and carbon source depletion induce MAGEA6 degradation by proteasomes." (PMID 32270762, 2020). "Cancer-specific mutations and glucose/glutamine depletion stimulate proteasome-dependent MAGEA6 degradation." (PMID 32270762, 2020). "The inhibition of autophagy is released upon MAGEA6 degradation, which can be induced by nutrient deficiency or by acquisition of cancer-associated mutations." (PMID 32270762, 2020). "Interestingly, one of the candidate effectors of DDX17 protein that we identified in this study was MAGEA6, which is not only associated with cancer but also involved in the degradation of AMPK." (PMID 36273228, 2022). "Autophagy can be suppressed by melanoma-associated antigen family A (MAGEA6) in PDAC cells (AsPC-1, BxPC-3, Capan-1, Capan-2, Panc-1, and MIA PaCa-2) and this suppression is released upon MAGEA6 degradation induced by nutrient deficiency or by the acquisition of cancer-associated mutations." (PMID 33198082, 2020). "Recently, an International Cancer Genome Consortium (ICGC) study listed MAGEA6 among the top 16 significantly mutated genes across tumors in two of three computational methods used (Fisher combined p value test, p=0.07; likelihood ratio test, p=9.88E-05; convolution test, p=8.85E-05)." (PMID 32270762, 2020). "In addition, there is an urgent need to understand the impact of cancer-specific mutations in MAGEA6 on tumor aggressiveness and on immunotherapy strategies." (PMID 32270762, 2020). "Immunohistochemistry (IHC) was then performed on cancer tissue microarrays (TMAs) from the Ren Ji cohort (N = 127) to assess MAGEA6 expression." (PMID 40145793, 2025). "MAGEA6 functions as a ubiquitin ligase physiologically, and normally is expressed only in the male germline, but also can be re-activated in human cancers." (PMID 36713306, 2023). "The degradation of MAGEA6 through ubiquitin proteasome pathway in late-stage disease revokes autophagy and further promotes cancer progression." (PMID 32270762, 2020). "While additional work is needed to validate these candidate oncogenes, including assessing variant activity compared with wild type, MAGEA6 and BST1 have both been previously implicated in cancer." (PMID 26806015, 2016). "A total of 145 DEGs were found to be involved in both cancer progression and drug resistance; among them, MAGEA6 log2 FC was most significantly expressed in TCGA, and significant differences were also found in GSE26459/GSE16179 (suggesting involvement in drug resistance)." (PMID 39370446, 2024). "Interestingly, known CTAs, such as MAGEA3, MAGEA1, DSCR8, MAGEC2, and MAGEA6, tended to be identified in the largest number of cancer types." (PMID 39561714, 2024). "Given the importance of autophagy and ferroptosis as master regulator in human cancer, MAGEA6/AMPKα1 may provide insights into slowing cancer cell progression and therapeutic targets." (PMID 39370446, 2024). "MAGEA6 is a known targeted anti-cancer therapy for MM and has predicted poor outcomes." (PMID 35565356, 2022). "Cancer patients with high MAGEA6 expression exhibit poor prognosis." (PMID 34885040, 2021). "We next sought to examine the role of MAGEA6 over the course of cancer progression in patients." (PMID 32270762, 2020). "Pineda and colleagues have recently identified MAGEA6 as a cancer-specific AMPKα1 ubiquitin ligase." (PMID 29156790, 2017). "In neoplastic cells, MAGEA6 and TRIM28 are combined to form a cancer-specific ubiquitin ligase, that leads to inhibition of the AMPK signaling pathway, and in HCC induced the stemness maintenance and selfrenewal of stem cells." (PMID 36713306, 2023). "MAGEA2, MAGEA3, MAGEA4, MAGEA6, and MEGEA12, members of the MAGE family, have been studied for their potential for cancer immunotherapy." (PMID 37655157, 2023).
cancer (continued). "The relationship between MAGE-A proteins and ubiquitination is well known; for example, MAGEA3 and MAGEA6 form an E3 ubiquitin ligase complex with TRIM28, which participates in the survival of cancer cells by degrading AMPKa1." (PMID 34202157, 2021). "MAGEA6 and CTAG2 are expressed in testis, and in very low levels in placenta but are observed to be highly expressed in NSCLC and various cancer types." (PMID 34048178, 2021). "MAGEA6 and TRIM28 was combined to form a cancer-specific ubiquitin ligase that inhibited AMPK signaling pathway and induced the stemness maintenance and self‐renewal of HCC stem cells." (PMID 32514252, 2020). "Since cancer cells often require increased amounts of nutrients, such as glucose and glutamine, to sustain the enhanced metabolic pathways required for high proliferation rates, we tested whether glucose and glutamine contributed to maintaining MAGEA6 protein levels." (PMID 32270762, 2020). "Examples of biclusters from this category include the biclusters consisting of genes from the Cancer-Testis antigens family—MAGEA2, MAGEA3, MAGEA6, MAGEA10, CSAG1, CSAG2, CSAG3 (Xq28)/CT45A3, CT45A5, CT45A6 (Xq26.3)." (PMID 31216036, 2019). "The highest average expression values, calculated across all cancer samples, have candidate tumor-specific antigens ACTL8 (ranked 2nd), MAGEA6 (ranked 14th) and C6orf15 (ranked 8th) with a normalized count expression of 2167.8, 981.4 and 787.0 respectively." (PMID 31069014, 2019). "Genes such as MAGEA3 and MAGEA6 contributed targets for 7 cancer types each, while genes such as UMODL1, NLRP4, MAGEC2, ANKRD30A, and GPRC6A contributed targets for only 1 cancer type." (PMID 27439771, 2016). "Notable exclusions include the cancer/testis antigens MAGEA1, MAGEA3, MAGEA6, GAGE1, GAGE2, GAGE4 and GAGE5, which were originally identified as being strongly upregulated in the PR subgroup but are not upregulated in our PTTG1 high patients." (PMID 26445238, 2015). "Although MAGEA6 is only expressed in the testis, we found that MAGEA6 is expressed at a moderate level in AML cells, which is consistent with reports that MAGEA6 is re-expressed in cancer cells." (PMID 38378601, 2024). "MAGEA6 and MAGEA11 through UALCAN database based on cancer genome atlas (TCGA) were reported." (PMID 35022469, 2022). "Indeed, transcripts for a number of antigens such as CTAG2, MAGEA3, and MAGEA6, which are normally expressed in testis and are immunogenic when aberrantly expressed in cancer tissue, were strongly expressed in a subset of IE1, but not IE2, samples." (PMID 36609566, 2023). "Similarly, expression of MAGEA3, MAGEA6 and MAGEA12 was greater than 3-fold in all cancer lines, regardless of origin, when compared to HEK cells." (PMID 32760472, 2020).
tumor (32 papers, 2013 to 2025). "MAGEA6 mutations and expression variation manipulate autophagy to promote tumor progression at different stages." (PMID 32270762, 2020). "We posited that the tumorigenicity of MAGEA6 and its autophagy suppression then subside as the tumor grows owing to spontaneous gene mutations and nutrient stress." (PMID 32270762, 2020). "In the HCC Hep3B cell line, miR-448 works as a tumor suppressor to inhibit stem markers’ expression and tumorsphere formation by reducing melanoma-associated antigen 6 (MAGEA6) mRNA expression." (PMID 31861404, 2019). "Furthermore, we also found that autophagy inhibitors (chloroquine, CQ) reversed the decreases of IC50 value caused by MAGEA6 depletion, indicating that MAGEA6 regulates tumor chemo-sensitivity via modulating autophagy." (PMID 39370446, 2024). "These included MAGEA3, MAGEA6 and MAGEA10, all cancer‐testis antigens previously associated with higher tumour grade, stage, and risk of invasion in NMIBC." (PMID 41425537, 2025). "We also examined the differences in MAGEA3 and MAGEA6 expression between tumor tissues and adjacent normal tissues." (PMID 41452900, 2025). "Further, we investigated the function of MAGEA6 on DOX sensitivity in vivo using a xenograft tumor model." (PMID 39370446, 2024). "Above all, we believed that MAGEA6 regulates tumor chemo-sensitivity via negatively modulating autophagy." (PMID 39370446, 2024). "The Cu-PS, a 5-genes (C7, MAGEA6, HK2, CYP26B1 and EPO) signature, was significantly associated with TNM stage, tumor mutational burden (TMB), drugs sensitivity, and immunotherapies response." (PMID 36250008, 2022). "MAGEA6 was identified as an oncogene and can promote tumor progression via activating the AMPK signaling pathway." (PMID 34676211, 2021). "Downregulation of AMPK by MAGEA6 led to significant decrease in autophagy and upregulation of mTOR, facilitating tumor growth." (PMID 34885040, 2021). "The study identified two MAGEA6 mutations, MAGEA6N254I (tumor specimen PACA-86-T) and MAGEA6H305fs*>7 (tumor specimen ICGC_0050_TD), in PDAC patients." (PMID 32270762, 2020). "Although our study mainly focused on the tumor biology of a few MAGEA6 variants, the MAGE family involves more than 40 genes classified as CTA genes, broadly expressed in many tumor types." (PMID 32270762, 2020). "Using xenograft mouse models, we demonstrated that inhibition of autophagy is critical for tumor initiation whereas reinstitution of autophagy as a consequence of MAGEA6 degradation contributes to tumor progression." (PMID 32270762, 2020). "Given MAGEA6's role in tumor migration and invasion, we investigated whether YY1 contributes to these processes." (PMID 40145793, 2025). "In this study, we demonstrated that: 1) CRC patients with PNI showed significantly shorter DSS and DFS, and PNI correlated with tumor infiltration depth, distant metastasis, AJCC stage, and tumor size; 2) MAGEA6 was identified as a critical regulator of PNI in CRC." (PMID 40145793, 2025). "Additionally, the expression of MAGEA3 and MAGEA6 was higher in tumor tissues compared to adjacent normal tissues." (PMID 41452900, 2025). "Knockdown of MAGEA6 was shown to reduce tumor growth in mice." (PMID 39409926, 2024). "Notably, for another downregulated gene, MAGEA6 (log2FC = −2.58), a role in tumor transformation and tumor progression was recently demonstrated." (PMID 36829477, 2023). "In support of this contention, knockdown of ATG7 and VPS34, key players for autophagy activation, suppressed tumor growth induced by MAGEA6 downregulation, consistent with autophagy activity playing a key role in promoting tumor growth in response to MAGEA6 depletion in BxPC-3." (PMID 32270762, 2020). "MAGEA6 is generally expressed in the male testis, but is re-activated in many tumor cells." (PMID 32514252, 2020).
tumor (continued). "Collectively, our in vivo data and the patient survival analysis strongly support the hypothesis that wild-type and mutant MAGEA6 play distinct roles to promote tumor initiation and development at different disease stages." (PMID 32270762, 2020). "Under the same theory, the reactivation of autophagy induced by low MAGEA6 expression may provide extra intracellular catabolic capability to continuously downregulate MAGEA6 targets and sustains tumor development." (PMID 32270762, 2020). "Additionally, tumor growth was further remarkably reduced in the sh-MAGEA6 + DOX group (P < 0.001)." (PMID 39370446, 2024). "In conclusion, both in vitro and in vivo experiments demonstrated the significant impact of MAGEA6 on CRC cells, underscoring its crucial role in tumor progression." (PMID 40145793, 2025). "Based on RNA-seq data from TCGA-STAD, tumor tissues exhibited significantly elevated MAGEA3 and MAGEA6 expression compared to normal tissues." (PMID 41452900, 2025). "DAC treatment of tumor cells again resulted in the induction of MAGEA1, MAGEA3/MAGEA6, or MAGEA9 expression as validated by qPCR." (PMID 40791813, 2025). "A significant increase in UCK2, HMMR, and MAGEA6 expression and a significant decrease in CXCL8, EPO, PPARGC1A, FTCD, and CFHR3 expression was observed in tumor tissues." (PMID 38694506, 2024). "MAGEA6, as the most significantly expressed gene, was analyzed by RT-qPCR, western blotting and immunohistochemistry assay in TNBC cell lines and tumor tissues." (PMID 39370446, 2024). "MAGEA6, as one of the MAGE family members, is a proto-oncogene whose elevated expression is involved in tumor growth and progression via affecting signaling pathways or potential mechanisms." (PMID 39370446, 2024). "While studying the human MAGEA6/GABRA3 gene locus, we observed that DNA hypomethylation in tumor cells can lead to the activation of a long transcript (CT-GABRA3) that overlaps downstream promoters (GABRQ and GABRA3) and triggers their hypermethylation." (PMID 34462486, 2021). "In consonance with its role in autophagy suppression, MAGEA6 expression transformed HPDE cells, induced xenograft tumor growth, and led to poor survival." (PMID 32270762, 2020). "(A) Tumor volume plot (50 d after injection) and Kaplan-Meier survival plot (B) of xenograft assay using HPDE-iKRAS cells expressing GFP (Vec) or MAGEA6 (five mice, two injections each, N = 10)." (PMID 32270762, 2020). "MAGEA6 downregulation and AMPK activation were detected in Lnc-THOR-silenced/-KO A172 tumor tissues." (PMID 31727877, 2019). "Targeting the MAGEA6/YY1/CXCL1‐SC axis may provide a promising strategy to inhibit PNI and tumor progression, ultimately improving patient prognosis." (PMID 40145793, 2025). "Genes involving the extracellular space and plasma membrane regulators were increased in aggressive MSI‐H CRC tumors, and tumor antigens (MAGEA3, MAGEA6, MAGEA9B, or MAGEC2) involving in the transcriptional and post‐translational regulations were represented in the aggressive MSI‐H signature." (PMID 39322998, 2025). "Knockdown of MAGEA6 significantly reduced CRC cell migration, invasion, and PNI both in vitro and in vivo; 3) MAGEA6 promotes YY1 deubiquitination, enhancing CXCL1 expression and SC recruitment, while also driving tumor cell EMT." (PMID 40145793, 2025). "To assess whether MAGE genes were induced to levels that could be relevant for T-cell-mediated recognition, we compared the relative expression levels of MAGEA1, MAGEA3/MAGEA6, and MAGEA9 after DAC induction in healthy cells to the relative expression levels in tumor cells." (PMID 40791813, 2025). "MAGEA6 interacts with the transcription factor Yin‐Yang 1 (YY1), which subsequently increases the secretion of CXCL1 by CRC cells, facilitates the recruitment of CRC cells to SCs, while also enhancing tumor cell invasiveness through epithelial‐mesenchymal transition (EMT), ultimately promoting PNI." (PMID 40145793, 2025).
tumor (continued). "In agreement with the anti-tumorigenic role of MAGEA6 at a late disease stage, knockdown of MAGEA6 in the transformed PDAC cell line BxPC-3, which has high endogenous wild-type MAGEA6 expression, dramatically increased tumor volume compared with xenografts without MAGEA6 knockdown." (PMID 32270762, 2020). "We next assessed whether the aberrant chromatin status of the Xi also translated into X-linked gene reactivation by assessing XIST together with HDAC8, ATRX, MAGEA6, and TBL1X expression on fresh tumor stamps (including those analyzed above) or tumor-tissue cryosections." (PMID 25653311, 2015). "For one C/T antigen gene (MAGEA6), we used RNA FISH to show that this aberrant expression usually originated from the active rather than the inactive X in tumor cells." (PMID 25653311, 2015).
MAGEA6 also shares sentences with these, for which no sentence is quoted: ovarian carcinoma (5 papers); gastric cancer (3); acute myeloid leukemia (2); colon carcinoma (2); bladder tumor (1); esophageal adenocarcinoma (1); female reproductive organ tumors (1); invasive breast carcinoma (1); lung squamous cell carcinoma (1); metastatic carcinoma (1); non-small cell lung carcinoma (1); pancreatic cancer (1); pheochromocytoma (1); renal carcinoma (1); thymoma (1).